TRIM58 (tripartite motif containing 58)
Description:
E3 ubiquitin ligase induced during late erythropoiesis. Directly binds and ubiquitinates the intermediate chain of the microtubule motor dynein (DYNC1LI1/DYNC1LI2), stimulating the degradation of the dynein holoprotein complex. May participate in the erythroblast enucleation process through regulation of nuclear polarization.
Synonyms: BIA2
Tractability: Small molecule: a structure with a bound ligand is known.
Target class: Enzyme; Transferase
Gene: Protein-coding gene on chromosome 1 (247,857,187 to 247,880,138, forward strand). Ensembl gene ENSG00000162722.
Gene Ontology:
Molecular function: ubiquitin protein ligase activity; dynein heavy chain binding; dynein intermediate chain binding; zinc ion binding
Biological process: innate immune response; regulation of gene expression; positive regulation of erythrocyte enucleation; protein autoubiquitination; protein polyubiquitination; protein ubiquitination; regulation of nuclear migration along microtubule; ubiquitin-dependent protein catabolic process
Cellular component: cytoplasm
Genetic constraint (gnomAD): Loss-of-function variants: 35 observed, 23.41 expected, observed/expected ratio (o/e) 1.5, 90% interval 1.14 to 1.89. The upper end of that interval is the gene's LOEUF score, 1.89, which puts it in group 6 of 6, group 1 being the genes least tolerant of losing a copy. Missense variants: 641 observed, 528.88 expected, observed/expected ratio (o/e) 1.21, 90% interval 1.13 to 1.29. Synonymous variants: 265 observed, 224.4 expected, observed/expected ratio (o/e) 1.18, 90% interval 1.07 to 1.31.
Homologues: Orthologues: chimpanzee TRIM58 (98% identical), macaque TRIM58 (95% identical), dog TRIM58 (81% identical), pig TRIM58 (80% identical), rat Trim58 (79% identical), mouse Trim58 (79% identical), rabbit TRIM58 (72% identical), guinea pig Trim58 (63% identical). Paralogues in human: TRIM11 (41% identical), TRIM21 (40% identical), TRIM39 (38% identical), TRIM27 (37% identical), TRIM4 (36% identical), TRIM7 (35% identical), TRIM17 (35% identical), TRIML1 (33% identical), TRIM41 (33% identical), TRIM68 (32% identical), TRIM10 (31% identical), TRIM26 (31% identical), and 68 more.
Diseases named in the same sentence as TRIM58 in open-access papers:
TRIM58 is named in the same sentence as 31 diseases in open-access papers, as found by Europe PMC text mining. Sharing a sentence is not in itself a finding about the gene and the disease. The quoted sentences say what the papers report.
gastric cancer (8 papers, 2020 to 2025). A primary or metastatic malignant neoplasm involving the stomach. "As reported in previous studies, TRIM58 downregulation was associated with inferior prognosis and promoted malignancy in several tumors including gastric cancer, colorectal cancer, and lung cancer." (PMID 36644609, 2023). "Tripartite motif-containing 58 protein (TRIM58) is a potential tumor suppressor protein in gastric cancer, where it is presented in the downregulated form." (PMID 36769170, 2023). "It was concluded that TRIM58 increases β-catenin degradation to inhibit the progression of gastric cancer through ubiquitination-mediated mechanisms." (PMID 36769170, 2023). "As a member of the tripartite motif protein (TRIM) family, TRIM58 has been reported to function as a tumor-suppressor gene in many cancers including colorectal cancer and gastric cancer." (PMID 33833773, 2021). "Interestingly, inactivation of the ß-catenin signaling via ubiquitination due to suppression by TRIM58 was reported in gastric cancer cells." (PMID 40676219, 2025). "In addition, TRIM58 suppresses the tumor growth of gastric cancer cells by inactivation of b-catenin signaling via ubiquitination." (PMID 34222000, 2021). "Similar tumor suppressive effects mainly related to an inactivation of β-catenin by TRIM58 have been demonstrated in gastric cancer (GC) cell lines." (PMID 33066016, 2020). "Recent studies have reported that TRIM58 regulates epithelial–mesenchymal transition (EMT) via the Wnt/β-catenin pathway and may function as a tumor suppressor in some cancers, such as colorectal cancer and gastric cancer." (PMID 34435051, 2021).
colorectal cancer (7 papers, 2021 to 2023). A primary or metastatic malignant neoplasm that affects the colon or rectum. "This study aimed to investigate the underlying molecular mechanisms of TRIM58 in the development of colorectal cancer (CRC)." (PMID 37516854, 2023). "Aberrant gene methylation of TRIM58 has been shown in several malignancies including liver, lung, and colorectal cancer, induces silencing, and is associated with poor prognosis." (PMID 35445910, 2022). "It has been reported that decreased TRIM58 expression is associated with a poor patient outcome and promotes invasion of colorectal cancer cells." (PMID 34222000, 2021). "The expression of TRIM58 in the human colorectal cancer was significantly inhibited and negatively correlated with the severity of colorectal cancer." (PMID 34222000, 2021).
lung adenocarcinoma (6 papers, 2017 to 2025). A carcinoma that arises from the lung and is characterized by the presence of malignant glandular epithelial cells. "Besides, a decrease in the expression of TRIM58 via hypermethylation has been strongly associated with cancer progression in patients with early stage lung adenocarcinoma." (PMID 33833773, 2021). "As a member of tumor suppressor genes (TSGs), previous research indicated that even in early stage of lung adenocarcinoma (LADC), aberrant promoter CpG island methylation resulted in robust expression suppression of TRIM58, which stimulated early carcinogenesis of LADC." (PMID 36644609, 2023). "Moreover, TRIM58 dysregulation stimulates early stage human lung adenocarcinoma, regardless of the presence or absence of tobacco smoking-induced epigenetic field defects." (PMID 37516854, 2023).
lung carcinoma (4 papers, 2020 to 2023). "Receiver operating characteristic curve analysis demonstrated that TRIM58 may be a promising early diagnostic indicator of lung cancer." (PMID 34434284, 2021). "ROC analysis was used to evaluate the diagnostic value of TRIM58 in lung cancer." (PMID 34434284, 2021). "Compared with the control group (scramble siRNA), TRIM58 silencing potently accelerated the migration of lung cancer cells, whereas overexpression of TRIM58 exerted the opposite effect." (PMID 34434284, 2021). "The MTS assay indicated that the silencing of TRIM58 promoted the proliferation of lung cancer cells." (PMID 34434284, 2021). "In conclusion, through DNA methylation-based profiling screening, the present study demonstrated that TRIM58 methylation has promise as a biomarker for the early diagnosis of lung cancer." (PMID 34434284, 2021). "Integrating the results of high-throughput screening, focusing on TRIM58, which was hypermethylated and downregulated in lung cancer." (PMID 34434284, 2021). "In the present study, high-throughput screening and independent validation demonstrated that TRIM58 was hypermethylated and downregulated in lung cancer compared to normal tissues." (PMID 34434284, 2021). "ROC analysis performed in the present study revealed that TRIM58 had a strong predictive value for the early diagnosis of lung cancer." (PMID 34434284, 2021). "In contrast, the overexpression of TRIM58 significantly inhibited the proliferation and migration of lung cancer cells and promoted apoptosis." (PMID 34434284, 2021). "Cell experiments confirmed the role of TRIM58 as a tumor suppressor gene in lung cancer and overexpression of TRIM58 inhibited the malignant phenotype of tumors." (PMID 34434284, 2021). "In this article, we demonstrated that TRIM58 suppression was a characteristic in lung cancer cells." (PMID 36644609, 2023). "The results indicated that TRIM58 was a novel tumor suppressor gene in lung cancer." (PMID 34434284, 2021). "Previous studies have shown that TRIM protein may serve an important role in tumorigenesis; however, the mechanism by which TRIM58 participates in the regulation of lung cancer remains unclear." (PMID 34434284, 2021). "Silencing TRIM58 accelerated the proliferation and migration of lung cancer cells." (PMID 34434284, 2021). "In addition, flow cytometry analysis demonstrated that TRIM58 overexpression promoted the apoptosis of lung cancer cells compared with empty pcDNA3.1 vector." (PMID 34434284, 2021). "In addition, the present study attempted to explore the signaling pathways related to TRIM58 in lung cancer to understand the potential mechanisms by which TRM58 participates in the regulation of tumor progression." (PMID 34434284, 2021). "There are few reports of the molecular mechanism of TRIM58's regulatory role in lung cancer." (PMID 34434284, 2021). "In addition, the present study analyzed the role of TRIM58 in tumorigenesis and development in lung cancer A549 cells." (PMID 34434284, 2021). "Thus, it explained the potential mechanism of suppressed expression of TRIM58 in lung cancer, and such discovery also indicated that targeted aberrant TRIM58 methylation could be novel therapeutic target in future lung cancer treatment development." (PMID 36644609, 2023). "The results revealed that tripartite motif containing 58 (TRIM58), a potential tumor suppressor gene exhibited high methylation and low expression in lung cancer tissue samples compared with normal tissues." (PMID 34434284, 2021).
breast carcinoma (3 papers, 2019 to 2024). "Besides, it was found that TRIM58 interacts with DDX3 and negatively regulates the expression of DDX3, leading to ubiquitination degradation of DDX3 and thus increasing adriamycin resistance in breast cancer cells." (PMID 36249749, 2022).
hepatocellular carcinoma (3 papers, 2017 to 2025). A malignant tumor that arises from hepatocytes. "Furthermore, TRIM58 has also been reported to be associated with DNA methylation in hepatocellular carcinoma, and hypermethylation of TRIM58 is strongly associated with worse survival in patients with hepatocellular carcinoma after hepatectomy." (PMID 37516854, 2023). "Very recently, hypermethylation was found to correlate with decreased TRIM58 expression in hepatocellular carcinoma (HCC) cells relative to paired adjacent liver tissues, although no functional characterization was observed in HCC cells." (PMID 27926516, 2017).
colon cancer (2 papers, 2022 to 2023). "In our study, based on the colon cancer immune gene datasets, we used WGCNA to identify 21 immune-related hub genes affecting patients’ OS and constructed IRGPI based on 8 independent OS prognostic factors (UCN, TRIM58, RBCK1, TPM2, CD36, NMB, PPARGC1A, and LGALS4)." (PMID 35572595, 2022).
lung squamous cell carcinoma (2 papers, 2019 to 2020). "We previously identified that TRIM58 is a novel prognostic-related methylation-driven gene in lung squamous cell carcinoma." (PMID 31805986, 2019). "Here, using SMART App, we can easily find that TRIM58 (cg10983544) is much hyper-methylated in stage II group in lung squamous cell carcinoma, indicating its clinical relevance (p value = 0.016)." (PMID 31805986, 2019).
osteosarcoma (2 papers, 2020 to 2024). A usually aggressive malignant bone-forming mesenchymal neoplasm, predominantly affecting adolescents and young adults. "In osteosarcoma cells, TRIM58 interacts with pyruvate kinase M2 (PKM2) and increases PKM2 polyubiquitination, thereby inhibiting PKM2 expression and activity." (PMID 39062505, 2024). "Evidence suggests that TRIM58 suppresses osteosarcoma cell progression by negatively regulating energy metabolism in osteosarcoma cells." (PMID 39062505, 2024). "Overexpression of TRIM58 significantly inhibits osteosarcoma cell growth and reduces glucose transport and lactate secretion." (PMID 39062505, 2024). "Furthermore, TRIM58 has been found to be underexpressed in human osteosarcoma tissues." (PMID 39062505, 2024). "However, the biological function of TRIM58 in osteosarcoma (OS) is still less identified." (PMID 32219144, 2020).
pancreatic cancer (2 papers, 2021 to 2025). "The key findings of the current study highlights ZNF804A, ZFP82, TRIM58, SOX17, and C12orf42 as hypermethylated/downregulated genes in pancreatic cancer associated with the development and progression of pancreatic cancer through their modulation of specific pathways." (PMID 33833773, 2021). "Taken together, the key findings of the current study demonstrate that ZNF804A, ZFP82, TRIM58, SOX17, and C12orf42 are hypermethylated/downregulated genes in pancreatic cancer and may be associated, through their modulation of specific pathways, with unfavorable pancreatic cancer prognosis." (PMID 33833773, 2021). "In the current study, 5 hypermethylated/downregulated genes in pancreatic cancer were identified, including ZNF804A, ZFP82, TRIM58, SOX17, and C12orf42, all of which were found to be correlated with the poor survival of pancreatic cancer patients." (PMID 33833773, 2021). "Univariate Cox model and Kaplan–Meier method revealed that, among 31 MeDEGs, 5 hypermethylated/downregulated genes (ZNF804A, ZFP82, TRIM58, SOX17, and C12orf42) were correlated with poor survival of patients with pancreatic cancer." (PMID 33833773, 2021).
thyroid cancer (2 papers, 2021 to 2026). "However, the current proteomics data demonstrated that AUF1 knockdown increased TRIM58 expression, simultaneously b-catenin was also increased in thyroid cancer cells." (PMID 34222000, 2021). "Overall, our results suggest that AUF1 affecting thyroid cancer cells via regulating the expression of ZBTB2 and subsequent TRIM58 expression in vitro." (PMID 34222000, 2021). "Moreover, online database as well as the local data demonstrated the positive coexpression of TRIM58 and ZBTB2 in thyroid cancer tissues." (PMID 34222000, 2021).
ulcerative colitis (2 papers, 2021). An inflammatory bowel disease involving the mucosal surface of the large intestine and rectum. "Low levels of TRIM58 were identified in colons of ulcerative colitis patients, suggesting that restriction of innate immune activation by TRIM58-dependent TLR2 degradation is required to prevent excessive inflammation." (PMID 34356615, 2021). "Another study showed that TRIM58 might protect against the transduction of intestinal mucosal inflammation by inhibiting abnormal TLR2 signaling and serve as a potential therapeutic target in autoimmune diseases, such as ulcerative colitis." (PMID 34435051, 2021).
benign meningioma (1 paper, 2022). A grade I, slowly growing meningioma. "Although median expression scores were 20 in both high-grade and benign meningiomas, the Kruskal–Wallis test revealed a statistically significant correlation between histology and TRIM58 expression (p = 0.034)." (PMID 35445910, 2022).
colon adenocarcinoma (1 paper, 2023). "TRIM58 expression was significantly lower in colon adenocarcinoma tissues than in normal tissues." (PMID 37516854, 2023).
hemoglobin disorders (1 paper, 2024). "Here, we have used a general strategy to assess the capability of two erythroid cell–enriched E3 ubiquitin ligases, TRIM10 and TRIM58, to degrade a POI, BCL11A, which is a validated target for reactivation of HbF in hemoglobin disorders." (PMID 39675716, 2024).
liver cancer (1 paper, 2025). An epithelial or non-epithelial malignant neoplasm that arises from the liver. "Although no consistent patterns for the Δβ of ALX3, NPTX2, and TRIM58 were observed across the stages, these three genes were stably hypermethylated in nearly all stages, except for NPTX2 at the fourth stage in liver cancer." (PMID 39944136, 2025).
meningioma (1 paper, 2022). A generally slow growing tumor attached to the dura mater. "Expression of TRIM58 was found in the majority of analyzed meningioma samples." (PMID 35445910, 2022). "In conclusion, this is the first study reporting the expression of the oncogenes TRIM58, FAM84B, ELOVL2, and DIO3 in meningiomas and correlations with histology and prognosis." (PMID 35445910, 2022). "Expression of the corresponding onco- and tumor suppressor genes TRIM58, FAM84B, ELOVL2, MAL2, LMO3, and DIO3 were analyzed and scored by immunohistochemical staining and RT-PCR in samples of 111 meningioma patients." (PMID 35445910, 2022). "Recent in vitro analyses revealed a dose-dependent efficiency of DCT also in high-grade meningiomas, with specific DNA demethylation of several onco- or tumor suppressor genes (TRIM58, FAM84B, ELOVL2, MAL2, LMO3, DIO3), which have been hardly investigated in meningiomas yet." (PMID 35445910, 2022).
papillary thyroid cancer (1 paper, 2021). "In overall, we suggest that AUF1 may regulate the expression of ZBTB2 by binding to ZBTB2 3’-UTR, affecting the stability of ZBTB2 mRNA, which in turn affects the expression of TRIM58 and regulates the proliferation, migration, and invasion of papillary thyroid cancer cells." (PMID 34222000, 2021).
thyroid tumor (1 paper, 2021). A benign or malignant neoplasm affecting the thyroid gland. "Results showed that AUF1 expression was increased, while ZBTB2 and TRIM58 was reduced in human thyroid tumors, when compared with those in peripheral normal tissues." (PMID 34222000, 2021).